PDCD7 (programmed cell death 7)
Description:
Promotes apoptosis when overexpressed.
Synonyms: hES18; ES18; 59K
Tractability: Small molecule: a structure with a bound ligand is known. Antibody: the Human Protein Atlas places it where antibodies can reach. PROTAC: ubiquitination databases record sites on it; its protein half-life has been measured.
Gene: Protein-coding gene on chromosome 15 (65,117,379 to 65,133,808, reverse strand). Ensembl gene ENSG00000090470.
Subcellular location: Nucleus
Subcellular location (Human Protein Atlas): Plasma membrane; Nucleoli
Pathways (Reactome):
Metabolism of RNA: mRNA Splicing - Minor Pathway
Gene Ontology:
Biological process: mRNA splicing, via spliceosome; response to glucocorticoid; RNA splicing; spliceosome conformational change to release U4 (or U4atac) and U1 (or U11)
Cellular component: spliceosomal complex; U11/U12 snRNP; U12-type precatalytic spliceosome; U12-type spliceosomal complex; nucleoplasm; nucleus
Genetic constraint (gnomAD): Loss-of-function variants: 37 observed, 33.36 expected, observed/expected ratio (o/e) 1.11, 90% interval 0.85 to 1.46. The synonymous counts are far from expectation, so gnomAD's model fits this gene poorly and the ratio says little. Missense variants: 629 observed, 529.29 expected, observed/expected ratio (o/e) 1.19, 90% interval 1.11 to 1.27. Synonymous variants: 296 observed, 231.73 expected, observed/expected ratio (o/e) 1.28, 90% interval 1.16 to 1.41.
Homologues: Orthologues: chimpanzee PDCD7 (100% identical), dog PDCD7 (94% identical), pig PDCD7 (93% identical), macaque PDCD7 (93% identical), mouse Pdcd7 (91% identical), rat Pdcd7 (84% identical), rabbit PDCD7 (83% identical), guinea pig PDCD7 (70% identical), tropical clawed frog pdcd7 (48% identical), zebrafish pdcd7 (39% identical). Paralogues in human: COL8A2 (14% identical), COL8A1 (14% identical), COL10A1 (13% identical), C1QC (11% identical), C1QTNF9 (11% identical), C1QTNF9B (10% identical), COL19A1 (10% identical), OTOL1 (10% identical), C1QB (9% identical), ADIPOQ (9% identical), C1QTNF5 (8% identical), C1QTNF2 (8% identical), and 11 more.
Diseases named in the same sentence as PDCD7 in open-access papers:
PDCD7 is named in the same sentence as 6 diseases in open-access papers, as found by Europe PMC text mining. Sharing a sentence is not in itself a finding about the gene and the disease. The quoted sentences say what the papers report.
acute myeloid leukemia (2 papers, 2014 to 2021). Acute myeloid leukemia (AML) is a group of neoplasms arising from precursor cells committed to the myeloid cell-line differentiation. "However, the specific function of PDCD7 in human is still unknown, although several studies have reported that human PDCD7 may related to the acute myeloid leukemia (AML)." (PMID 33849599, 2021).
atrial fibrillation (1 paper, 2025). A disorder characterized by an electrocardiographic finding of a supraventricular arrhythmia characterized by the replacement of consistent P waves by rapid oscillations or fibrillatory waves that vary in size, shape and timing and are accompanied by an irregular ventricular response. "The WMH TWAS also identified genes associated with AD (ARMS2), atrial fibrillation (NEURL and GJC1), innate immunity (EFTUD2), and apoptosis and neurodevelopment (PDCD7, FBXO31, and ClpX)." (PMID 40141087, 2025).
tumor (3 papers, 2014 to 2023). "In our present study, AML patients had higher PDCD7 compared to non-malignant controls, and PDCD7 was positively correlated to bone marrow blast counts, which indicating a correlation between tumor burden and PDCD7 expression in AML." (PMID 24416201, 2014). "The upregulation of miR-134 reduces PDCD7 and attenuates PDCD7-mediated tumor suppression." (PMID 34440464, 2021).
PDCD7 also shares sentences with these, for which no sentence is quoted: breast carcinoma (1 paper); myeloid neoplasm (1); virus infection (1).